CXCR4 (C-X-C motif chemokine receptor 4)
Diseases named in the same sentence as CXCR4 in open-access papers (continued):
Sharing a sentence is not in itself a finding about the gene and the disease.
chronic pancreatitis (1 paper, 2016). A chronic inflammatory process causing damage and fibrosis of the pancreatic parenchyma. "Next, we investigated the expression of CXCR4 in stellate cells isolated from chronic pancreatitis patients and normal subjects in cultured primary human stellate cells, and also in human pancreatic sections." (PMID 27630579, 2016). "In contrast, as indicated by flow cytometry analysis, the mean percentages of stellate cells expressing surface CXCR4 were significantly increased in chronic pancreatitis, as compared to normal cells." (PMID 27630579, 2016). "Here we provide evidence that Lyn activity is selectively increased in stellate cells during chronic pancreatitis, which leads to their hyperactive CXCR4-mediated migration, increased proliferation, and excessive collagen production, resulting in chronic fibrosis of pancreas." (PMID 27630579, 2016). "Chronic pancreatitis cells showed increased CXCR4-induced chemotaxis by ~three-fold as compared to normal cells, which could be blocked by treatment with AMD3100, a specific antagonist for the SDF-1 receptor CXCR4." (PMID 27630579, 2016). "Immunocolocalization studies (Section Materials and Methods) indicated the significant colocalization of CXCR4 with α–SMA (marker of activated stellate cells), reaching a ~15-fold increase in chronic pancreatitis tissues, as compared to normal pancreata." (PMID 27630579, 2016). "We then investigated the SDF-1/CXCR4-induced chemotactic response of chronic pancreatitis and normal stellate cells." (PMID 27630579, 2016). "This is important because the mean percentages of stellate cells expressing surface CCR5 (in addition to CXCR4) were significantly increased in chronic pancreatitis as compared to normal stellate cells (not shown), and CCR5 mediates Lyn signaling in other cellular systems." (PMID 27630579, 2016).
cleft palate (1 paper, 2023). Cleft palate is a fissure type embryopathy that affects the soft and hard palate to varying degrees. "This study aimed to investigate the regulation of Cxcr4 during palate development and provide a new etiology for the mechanism of cleft palate formation, in addition to offering a scientific basis for the prevention of cleft palate." (PMID 37628919, 2023).
colonic adenomas (1 paper, 2020). "A prior study reported CXCR4 protein was upregulated in CRC compared to colonic mucosa and colonic adenomas." (PMID 32110952, 2020).
colorectal adenocarcinoma (1 paper, 2025). The most common type of colorectal carcinoma. "We treated HT-29 human colorectal adenocarcinoma cells with UDCA and found that UDCA inhibited G protein-coupled receptor (GPCR) CXCR4 expression." (PMID 39804065, 2025).
Dandy-Walker malformation (1 paper, 2014). "Here we have demonstrated that the pathogenesis underlying Foxc1-dependent Dandy-Walker malformation, a major human neurodevelopmental disorder, is caused by loss of SDF1α-Cxcr4 mediated cerebellar radial glial proliferative and migrational scaffold function." (PMID 25513817, 2014). "The disproportionate mouse cerebellar phenotypes we report here with loss of Foxc1 and Cxcr4 beautifully model the CNS phenotype of Dandy-Walker malformation patients, where the cerebellum is disproportionately diminished in size and altered in morphology relative to other CNS structures." (PMID 25513817, 2014).
dermatomyositis (1 paper, 2015). Dermatomyositis (DM) is a type of idiopathic inflammatory myopathy characterized by evocative skin lesions and symmetrical proximal muscle weakness. "Our results conflict with those of authors who report detection by direct flow cytometry of CD105, CD90, and CXCR4 on MPs from mesenchymal stem cells and CD3, CD14 and CD19 on MPs from the plasma of polymyositis/dermatomyositis patients." (PMID 25978814, 2015).
dry eye (1 paper, 2018). "Again, these cell populations increased in dry eye patients, explaining the higher levels of CXCL12 and CXCR4 in patients suffering from DED." (PMID 29673232, 2018).
endometrial tumour (1 paper, 2025). "The proportion of suspected cancer stem cell population (CD133+CXCR4+ and CD133+CXCR4−) was found to be higher in primary cells established from type II endometrial tumour sample (5.7% and 74%) as compared to primary cells established from type I endometrial tumour sample (1.4% and 33%)." (PMID 40433700, 2025).
epidermodysplasia verruciformis (1 paper, 2019). A rare inherited genodermatosis characterized by chronic infection with human papillomavirus (HPV) leading to polymorphous cutaneous lesions and high risk of developing non melanoma skin cancer. "Examples of such diseases are TLR3, TRIF, or UNC93B1 deficiencies which predispose to HSV-1 encephalitis and epidermodysplasia verruciformis or CXCR4 deficiencies which predispose to HPV." (PMID 31191561, 2019).
erythroleukemia (1 paper, 2020). Acute erythroid leukemia characterised by the presence of at least 50% erythroid precursors and at least 20% myeloblasts in the bone marrow. "Here, we demonstrate that the alteration of iron homeostasis and the consequent increase of redox metabolism, mediated by the stable knock down of ferritin heavy chain (FtH), enhances the expression of CXCR4 in K562 erythroleukemia cells, thus promoting CXCL12-mediated motility." (PMID 32432042, 2020). "To achieve this goal, we defined the effects of FtH knock down in the induction of EMT markers, activation of CXCR4/CXCL12 signaling pathway and migration of K562 erythroleukemia cells, and further attempted to understand the molecular mechanisms involved." (PMID 32432042, 2020).
esophagogastric adenocarcinoma (1 paper, 2014). "Since cisplatin relies on ERK activation for bioactivity in some cells, in contrast to oxaliplatin, this might explain the chemosensitivity of VEGFR-3 and CXCR4 positive esophagogastric adenocarcinoma to FLP and not to FLO." (PMID 24981311, 2014).
Fanconi anemia (1 paper, 2025). Fanconi anemia (FA) is a hereditary DNA repair disorder characterized by progressive pancytopenia with bone marrow failure, variable congenital malformations and predisposition to develop hematological or solid tumors. "For instance, it has a positive clinical impact on ADA deficiency, Wiskott-Aldrich syndrome (WAS), Fanconi anemia, and in variants affecting DOCK8, ITGB2, or CXCR4." (PMID 40711587, 2025).
fluorosis (1 paper, 2024). "In this study, we investigated the role of the SDF-1/CXCR4 signaling axis and related inflammatory factors in fluorosis through in vitro experiments on human hepatic astrocytes (LX-2) cultured with sodium fluoride." (PMID 38905184, 2024). "In addition, the SDF-1/CXCR4 signaling axis was shown to activate the NF-κB signaling pathway to participate in the inflammatory response, suggesting that the SDF-1/CXCR4–NF-κB signaling pathway may play a role in the pathogenesis of fluorosis." (PMID 38905184, 2024). "Whether inflammatory factors such as SDF-1/CXCR4, IL-6, TNF-α, NF-κB, and IL-1β play a role in the hepatic system due to fluorosis deserves further exploration." (PMID 38905184, 2024). "Therefore, the present study aimed to further investigate the role of the CXCL12/CXCR4 signaling axis and the related inflammatory factors IL-1β, TNF-α, IL-6 and NF-κB in the mechanism of fluorosis-induced liver injury at the cellular level." (PMID 38905184, 2024).
genital warts (1 paper, 2021). "To date, mainly case reports or series were reported, showing that GATA binding protein 2 (GATA2) and CXC motif chemokine receptor type 4 (CXCR4) deficiencies are associated with genital warts." (PMID 34868076, 2021).
gestational diabetes (1 paper, 2021). Carbohydrate intolerance first diagnosed during pregnancy. "In placenta and/or pancreatic tissues of patients and animal models with gestational diabetes (GDM), the expression of miR-222 and NLR family pyrin domain containing 3 (NLRP3) inflammasomes were up-regulated while C-X-C chemokine receptor type 4 (CXCR4) was downregulated." (PMID 34199293, 2021).
hematoma (1 paper, 2021). A hematoma is a collection of blood from a vascular structure into an extravascular space. "The other is associated with T cell subcluster 6, which is a hematoma cluster emerging during rebleeding, and is defined by T cell effector genes like CXCR4, TXN, and CSTB (effector module score 2)." (PMID 33749664, 2021).
histiocytic lymphoma (1 paper, 2017). "Cellularly, both have been shown to potently inhibit SDF-1 mediated cell migration of human histiocytic lymphoma U937 cells and cell signaling mediated by SDF-1/CXCR4 such as activation of phospho-ERK and phospho-AKT." (PMID 29212254, 2017).
hyperplasia (1 paper, 2023). An abnormal increase in the number of cells in an organ or a tissue with consequent enlargement. "Hyperplasia may account for this increase as well as homing, which preponderantly depends on the SDF-1/CXCR4 axis with increased expression of CXCR4 in cancer cells and SDF-1 secretion by ASCs." (PMID 36766689, 2023).
hyperreactivity (1 paper, 2023). "It was reported that SDF-1/CXCR4 signaling was involved in hyperimmune response and airway hyperreactivity in asthmatic animals." (PMID 37443753, 2023).
inherited thrombocytopenia (1 paper, 2020). An instance of thrombocytopenia that is inherited. "SDF-1α-CXCR4 localized to lipid rafts in the platelet membrane trigger platelet reactivity, while decreased surface expression of CXCR4 in patients with inherited thrombocytopenia corroborates with impaired CXCL12/SDF1α-triggered platelet aggregation." (PMID 33114406, 2020).
ischemia reperfusion injury (1 paper, 2020). Adverse functional, metabolic, or structural changes in ischemic tissues resulting from the restoration of blood flow to the tissue (reperfusion), including swelling; hemorrhage; necrosis; and damage from free radicals. "In a rat model of ischemia-reperfusion injury, Ciullo and colleagues showed that the systemic administration of exosomes (genetically engineered to overexpress CXCR4–ExoCXCR4) derived from CXCR4-overexpressing (a transmembrane receptor—CD184) CPCs improve heart function." (PMID 32466282, 2020).
keratitis (1 paper, 2018). A corneal disease that is characterized by inflammation of the cornea. "This is the first report on the implication of CXCR4 blockade in cDC homing to the cornea in a murine model of keratitis." (PMID 30489627, 2018).
leiomyosarcoma (1 paper, 2025). An uncommon, aggressive malignant smooth muscle neoplasm, usually occurring in post-menopausal women. "The MIF-CD74 and CXCR4-MIF/CD74 showed higher co-expression levels in undifferentiated pleomorphic sarcoma than in leiomyosarcoma." (PMID 40831537, 2025). "Spatial transcriptomic data revealed that MIF-CD74 and CXCR4-MIF/CD74 showed a higher positive correlation in undifferentiated pleomorphic sarcoma than leiomyosarcoma." (PMID 40831537, 2025). "Spatial transcriptomic data showed that co-expression levels of MIF-CD74 and CXCR4-MIF/CD74 were positively correlated in undifferentiated pleomorphic sarcoma, whereas the correlation was low in leiomyosarcoma." (PMID 40831537, 2025).
liver failure (1 paper, 2023). A liver disease characterized by the liver losing or has lost all of its function. "An IL-1β pretreatment improved the homing efficacy of mesenchymal stem cells on liver failure through an increased CXCR4 expression." (PMID 36979628, 2023).
lung carcinoids (1 paper, 2015). "In contrast to many other tumor entities, the role of CXCR4 expression has not been evaluated in typical and atypical lung carcinoids so far, and there are only limited data available on CXCR4 expression in SCLC." (PMID 25671300, 2015).
lung NETs (1 paper, 2016). "Recent evidence demonstrated that CXCR4 is expressed in lung NETs and significantly correlated with negative patient outcome." (PMID 26934559, 2016).
lymph node diseases (1 paper, 2021). "For example, in patient 15 with PD after chemotherapy, despite a nearly 50% reduction of TLUCXCR4 and MTV CXCR4 from baseline, there were new emerging lymph node diseases detected by both 18F-FDG and 68Ga-pentixafor PET/CT at follow-up, consistent with the clinical response classification of PD." (PMID 34714390, 2021).
lymphocytic leukemia (1 paper, 2011). "Expression of functional CXCR4 has been reported in various types of cancer cells, but also in immune cells such as peripheral blood lymphocytes, unprimed T cells, dendritic cells and lymphocytic leukemia B cells, where CXCR4 mediates spontaneous migration beneath bone marrow and stromal cells." (PMID 21349176, 2011).
malignant tumor of the biliary tract (1 paper, 2020). "Moreover, an increase in the CXCR4 expression is shown to significantly lower the survival rate and CXCR4 knockdown is associated with the down-regulation of Wnt target genes and inhibition of progression of malignant tumor of the biliary tract." (PMID 32140709, 2020).
malnutrition (1 paper, 2026). Inadequate nutrition resulting from poor diet, malabsorption, or abnormal nutrient distribution. "T-cell sensitivity to glucocorticoids was required for elevated expression of CXCR4 and CCR7 in naïve CD4+ T cells during malnutrition." (PMID 41992943, 2026).
mastocytosis (1 paper, 2023). A clonal myeloproliferative neoplasm characterized by the proliferation and accumulation of neoplastic mast cells in one or multiple organs or organ systems. "This was accompanied by changes in the gene expression of adhesion molecules including CD44 and other molecules known to be chemoattractant molecules and receptors for mast cells such as CXCR4 and CCL2 (or MCP-1) and with reported functions in mastocytosis." (PMID 37025992, 2023).
membranous nephropathy (1 paper, 2022). "Furthermore, CXCR4 was also induced and colocalized with β-catenin in the glomeruli of human kidney biopsies from patients with proteinuric CKD including DN, FSGS and membranous nephropathy (MN)." (PMID 34976212, 2022).
microphthalmia (1 paper, 2023). Congenital or developmental anomaly in which the eyeballs are abnormally small. "A similar search of DR17 using the term microphthalmia resulted in 22 genes significant for the small eyes phenotype: Aldh1a3, Aff4, Bmp4, Cdk4, Cox6b1, Cxcr4, Dync1li1, Eef1d, Fgd1, Gne, Grh12, Mab21l2, Maf, Med13l, Mllt10, Mthfd2, Pex6, Phgdh, Ssr1, Stim1, Tdo2, and Vps26c." (PMID 36737727, 2023).
mineralocorticoid excess (1 paper, 2015). "In previous studies of mineralocorticoid excess we showed that CXCR4 antagonism attenuated the accumulation of CD4+ T-lymphocytes." (PMID 26214690, 2015).
muscular dystrophies (1 paper, 2020). "The critical role of muscle development and repair by the CXCR4/SDF-1 axis suggests that it may be a promising therapeutic target for particular muscular dystrophies." (PMID 33415110, 2020).
mycobacterial infection (1 paper, 2024). "We have previously identified an miRNA-mediated Cxcr4/Cxcl12 signalling axis which increased protective neutrophil responses in mycobacterial infection." (PMID 38307625, 2024).
myocardial diseases (1 paper, 2014). "TMP is widely used in the clinical therapy of ischemic cerebral and myocardial diseases in China, and whole-blood viscosity and platelet aggregation are used as prognostic indicators; the CXCR4/SDF-1 interaction is involved in these processes." (PMID 24505417, 2014).
myoma (1 paper, 2012). "CXCR4 in both the myoma model and the collagen assay was usually diffusely and strongly positive in both the HSC-3 and stromal cells." (PMID 23342263, 2012).
nasal polyps (1 paper, 2021). "In nasal polyps from patients with AR, the expressions of lnc-CXCL12-4, CXCL12, and CXCR4 were increased significantly compared to those from nasal polyps without AR." (PMID 33836777, 2021).
nephrolithiasis (1 paper, 2025). The presence of a calculus in the pelvis of the kidney; this is most often composed of mineral salts and proteins. "The pathogenesis of nephrolithiasis involves crystal deposition in renal tubules, interstitial plaque overgrowth, with CXCR4 potentially playing a role in monocyte infiltration and renal tissue damage." (PMID 40275250, 2025).
neurosarcoidosis (1 paper, 2024). A sarcoidosis that involves the nervous system. "Recent analysis of neurosarcoidosis cerebrospinal fluid and blood samples also identified increased CXCR4 signaling." (PMID 39225100, 2024).
nonalcoholic steatohepatitis (1 paper, 2018). "Interestingly, a previous report reveals that there is a tight contact between transcript factors NF-κB and CXCR4 expression in nonalcoholic steatohepatitis." (PMID 29849929, 2018).
obliterative bronchiolitis (1 paper, 2016). "Elevated levels of CXCR4 and CCR7 in respiratory epithelial lining fluid has been reported in patients with obliterative bronchiolitis (OB) after lung transplantation (LTP)." (PMID 27309347, 2016).
ocular adnexal lymphoma (1 paper, 2015). A non-Hodgkin lymphoma arising from the conjunctiva, lacrimal gland, lacrimal drainage apparatus, eyelids, or other orbital tissues around the eye. "In contrast, the malignant B cells in ocular adnexal lymphomas (10 FL, 9 DLBCL, 4 MCL and 28 MZL) expressed a profile of molecules suggesting a dynamic process of trafficking involving not only tissue retention but also egress via S1PR3 and homing back to extranodal sites via CXCR4/CXCL12 and α4." (PMID 25938000, 2015).
odontogenic cyst (1 paper, 2022). A cyst in the jaw that arises from tissues of tooth development. "Chemokine CXCL12 and its receptor CXCR4 participate in several physiologic and pathologic processes, but there is a lack of information about the role of these proteins in the pathogenesis of odontogenic cysts, as the available data are restricted to radicular cysts." (PMID 35582358, 2022). "Based on these findings and on the significant immunoexpression of CXCR4 in OKCs observed in the present study, we suggest a potential interaction of this receptor with non-canonical ligands in these odontogenic cysts." (PMID 35582358, 2022).
onchocerciasis (1 paper, 2009). Onchocerciasis is a form of filariasis, caused by the parasitic worm Onchocerca volvulus, transmitted by the black fly. "The neovascularisation was associated with a particular pattern of angio/lymphangiogenic factors in nodules of onchocerciasis patients, characterized by the expression of CXCL12, CXCR4, VEGF-C, Angiopoietin-1 and Angiopoietin-2." (PMID 20011036, 2009).
oncocytomas (1 paper, 2023). "In light of the sometimes challenging distinction between oncocytomas and ccRCCs in conventional imaging, an indication for this type of functional imaging may emerge given the high CXCR4 expression differences." (PMID 36982302, 2023). "An intriguing observation was the high cytoplasmic expression of CXCR4 in oncocytomas." (PMID 36982302, 2023). "Moreover, high cytoplasmic CXCR4 expression appeared as a characteristic in oncocytomas, which might be clinically meaningful in differential histopathology or functional imaging in the future." (PMID 36982302, 2023).
Opportunistic infection (1 paper, 2013). An infection that is caused by a pathogen that would generally not be able to cause an infection in a host with a normal immune system. "In this initial study, the only patient who did not normalize CXCR4 expression levels also failed to increase CD4+ T cell counts after IL-2 treatment and did not benefit clinically from the therapy, with continued occurrence of multiple opportunistic infections." (PMID 23383227, 2013).
Osteochondroma (1 paper, 2015). A common, benign cartiliginous neoplasm arising from the metaphysis of bone. "Positive CXCR4 expression was observed in four cases (20.00%) and β-catenin in five cases (25.00%) of osteochondroma." (PMID 26622806, 2015).
ovarian adenocarcinoma (1 paper, 2022). An adenocarcinoma that arises from the ovary. "The detection of liver micrometastases in an ovarian adenocarcinoma murine model was demonstrated by the CXCR4 targeted MRI imaging." (PMID 35145271, 2022).